LRIG1 (leucine rich repeats and immunoglobulin like domains 1)
Diseases named in the same sentence as LRIG1 in open-access papers (continued):
Sharing a sentence is not in itself a finding about the gene and the disease.
tumor (continued). "Additionally, LRIG1 is down-regulated in a variety of different tumour cell lines consistent with it being a tumour suppressor gene." (PMID 19779621, 2009). "There was a tight correlation between expression of Lrig1 and the degree of tumour differentiation." (PMID 18657901, 2008). "Increased LRIG1 copy number was associated with increased levels of LRIG1 mRNA (two of three tumours) and protein (four of four tumours) in the tumours compared to matched non-neoplastic breast tissue, as assessed by RT-PCR and western blot analysis." (PMID 16168117, 2005). "In 11 out of 28 tumours (39%), an increased number of LRIG1 signals were found." (PMID 16168117, 2005). "Of course, we cannot exclude that LRIG1 might have other functions, which for tumour promotion could dominate over its ERBB-antagonising effects." (PMID 16168117, 2005). "Four of these five tumours also displayed increased LRIG1 copy number." (PMID 16168117, 2005). "Thus, all of the tumours with increased LRIG1 copy number overexpressed LRIG1 as determined by western blot analysis, but also one tumour with normal LRIG1 copy number showed high levels of the protein by western blotting." (PMID 16168117, 2005). "Thus, further studies evaluating larger tumour materials and addressing the molecular function of LRIG1 are warranted." (PMID 14520461, 2003). "Interestingly, we have recently detected the downregulation of LRIG1 in some tumour cell lines of different origin." (PMID 14520461, 2003). "In conclusion, the underexpression of LRIG1 and the increase in EGFR/LRIG1 ratios found in RCC compared to the kidney cortex indicate that LRIG1 might be a tumour suppressor that counteracts the tumour-promoting function of EGFR." (PMID 14520461, 2003). "Since IL-17 induces the activation, proliferation, and epithelial-to-mesenchymal transition of quiescent Lrig1 expressing epithelial stem cells, and Lrig1 can be induced in cancer cells, IL-17 signaling could provide better survival of tumor cells after chemo- or radio-therapy." (PMID 37373022, 2023). "Notably, 2 CpG sites located in the gene body region of tumor suppressor genes, namely LRIG1 (leucine-rich repeats and immunoglobulin-like domains 1, cg26131019) and WWOX (WW domain–containing oxidoreductase, cg02171206), were among the associated loci in the unstratified analysis." (PMID 37930698, 2023). "Indeed, LRIG1 downregulation has prognostic impact across diverse tumour types." (PMID 35440669, 2022). "Given that ER-negative tumours show the most robust methylation, we performed Kaplan–Meier analysis on patients with ER-negative tumours to assess whether there was a correlation between LRIG1 CpG island methylation status and overall patient survival." (PMID 35440669, 2022). "Results suggest that AKAP12, APOL3, CXCL13, CXCL9, GBP4, and LRIG1 may act as tumor suppressors." (PMID 35677536, 2022). "However, since our genetic analyses in C. elegans indicated that negative regulation of RAS-MAPK signaling by LRIG/SMA-10 required the presence of EGFR/LET-23, we hypothesized that a tumor-suppressive function of LRIG1 may be exerted at the EGFR level." (PMID 33947959, 2021). "However, in a multivariate Cox regression analysis, neither LRIG1 loss nor LRIG1 gain was an independent prognostic factor after adjustment for the tumor subtype, tumor grade, LRIG1 copy number status, tumor size, nodal status, and age at diagnosis." (PMID 32448168, 2020). "In the analysis between the tumour tissues, mRNAs of LAMA3, E2F7, and IFI44 were more expressed in the tissues of the high-risk group than in those of low-risk group, whereas the expression levels of IFI44 and LRIG1 were lower in the high-risk group than in low-risk group." (PMID 31703415, 2019). "Conversely Lgr6 and Lrig1 tumours have associated stromal inflammation while Lgr5 tumours do not." (PMID 29807713, 2018). "Thus, Lrig1 is a bona fide tumor suppressor, as proposed in previous studies." (PMID 29317492, 2018).
tumor (continued). "In the present study, the association between LRIG expression and differentiation could not be shown, and non-keratinizing tumours were observed to have a higher LRIG1 expression, which was associated with a better prognosis." (PMID 28841699, 2017). "Lrig1 has prognostic value in several cancers, including GBM, through its role as a tumour suppressor regulating EGFR activity." (PMID 36420140, 2022). "This work highlights the clinical relevance of LRIG1 and the potential of the NTCU-induced LUSC model for functional assessment of candidate tumour suppressors and oncogenes." (PMID 34385275, 2022). "Following in vivo transplantation of either Lrig1 WT or Lrig1 KO GSCs into the striatum of NSG mice, we found that Lrig1 KO GSCs have greater tumour-initiating capacity and consequently mice showed reduced survival." (PMID 36420140, 2022). "We now show that downregulation of LRIG1 occurs early during LUSC evolution, before development of high-grade lesions and invasive tumours." (PMID 34385275, 2022). "While LRIG1 and LRIG3 are thought to be tumor suppressors, LRIG2 expression is mostly related to poor prognosis." (PMID 33786987, 2021). "Meanwhile, the human leucine rich repeats and immunoglobulin like domains 1 (LRIG1), belongs to the LRIG family of trans-membrane leucine rich proteins, and is a tumor suppressor which negatively regulates receptor tyrosine kinase signaling." (PMID 33893245, 2021). "On the contrary, the overexpression of LRIG1 alleviates the expression level of EGFR (either mutant or wild-type) and suppresses tumor expansion." (PMID 34576152, 2021). "The Lrig1-CreERT2/+;Apcfl/+ CRC model is very similar to the Gstp-null;ApcMin CRC model in terms of tumor onset, penetrance, multiplicity, anatomical location, and mortality." (PMID 32059662, 2020). "As expected, many DMGs that were hypermethylated and downregulated in CMT including TP63, LIFR, PLA2G16, LRIG1, STAT5A, and AKAP12 and have been known as tumor suppressors, were identified from high scoring (OncoScore > 50) CMT-DMRs." (PMID 32693820, 2020). "Regardless, LRIG1 still exerts tumor-suppressive functions in CRPC, suggesting that in treatment-failed tumors, LRIG1, positively regulated by AR and, possibly, by stemness factors, still functions to curb tumor development driven by these oncogenic factors." (PMID 31792211, 2019). "LRIG1 and LRIG3 show mostly tumor‐suppressive function, whereas LRIG2 frequently seems to act as an oncoprotein." (PMID 31580518, 2019). "We used a custom 60-gene panel enriched in gut-associated stem cell function together with 31 AOM-DSS-induced tumor samples (23 FFPE and 8 frozen), and 25 Apcfl;Lrig1-CreERT2 tumor samples (12 FFPE and 13 frozen), all of which were wild-type for Oct1." (PMID 31059499, 2019). "We further show that 1) AR directly transactivates LRIG1 through binding to several AR-binding sites in LRIG1 locus, and 2) LRIG1 dampens ERBB expression in a cell type-dependent manner and inhibits ERBB2-driven tumor growth." (PMID 31792211, 2019). "In contrast to above results, knocking down endogenous LRIG1 using pGIPZ-shLRIG1 in 3 AR+, AD PCa cells, VCaP, LAPC4, and LAPC9, significantly promoted tumor regeneration." (PMID 31792211, 2019). "Cell line screening showed the enrichment of cancer cells deprived of the expression of CD27, CEACAM1, CTLA4, LRIG1, PDCD1LG2, or TNFRSF18, suggesting their role as tumor suppressor." (PMID 31358815, 2019). "And tumor growth curve indicated that tumor growth rate was obviously suppressed by ISL, and the activity was reversed when LRIG1 was knocked down." (PMID 30081934, 2018). "We used immunohistochemistry to investigate LRIG1, LRIG2, and LRIG3 expression in tumour samples from a consecutive cohort of 70 PVC patients." (PMID 28841699, 2017). "These include genes involved in hematological system development such as SETBP1 and NRP1 and putative tumor suppressor genes such as PARD3 and LRIG1." (PMID 28806978, 2017).
tumor (continued). "Among those putative target candidates, five potential tumor suppressors, including CCNG2, FOXP1, NRG1, LRIG1, and TNFSF10, were shown to have a direct binding site with miR-130b-5p." (PMID 25888956, 2015). "The leucine rich repeats and immunoglobulin-like protein 1 (LRIG1) is a newly discovered negative regulator of epidermal growth factor receptor (EGFR) and a proposed tumor suppressor." (PMID 24709893, 2014). "LRIG1 negatively regulates multiple receptor tyrosine kinases signaling including the epidermal growth factor receptor (EGFR) and is a proposed tumor suppressor." (PMID 25353163, 2014). "Our findings support the suggestion that the upregulation of LRIG-1 suppresses advances in transformation, whereas complete deletion of LRIG-1 expression induces dedifferentiation of tumor cells." (PMID 24709893, 2014). "We found that MAP4 and Lrig1 were significantly downregulated in oral SCCs, while CD44, which has recently been reported to be a marker of tumour initiating cells in head and neck SCCs, and MCSP were highly upregulated." (PMID 18657901, 2008). "Downregulation of two markers, Lrig1 and MAP4, and upregulation of a third, MCSP, correlated with poor differentiation status and increased proliferation in primary tumours." (PMID 18657901, 2008). "Downregulation of MAP4 and Lrig1 and upregulation of MCSP were consistent features of SCC lines and primary tumours." (PMID 18657901, 2008). "LRIG1 has been proposed to interact with and counteract the effects of growth factor receptors such as EGFR/ERBB1, thereby functioning as a tumour suppressor." (PMID 16168117, 2005). "In this study, using quantitative PCR and immunohistochemistry, it was shown that the expression of LRIG1 was decreased and the ratio of EGFR/LRIG1 was increased in tumours vs normal tissue." (PMID 14520461, 2003). "In order to examine the mRNA expression of EGFR and LRIG1 in RCC, 31 tumour RNA samples and corresponding kidney tissue in eight of these patients were analysed by quantitative RT–PCR." (PMID 14520461, 2003). "When relating the LRIG1 and EGFR levels in tumour and kidney to each other, the ratio of EGFR/LRIG1 appeared high, especially in conventional RCCs." (PMID 14520461, 2003). "In addition, recent studies have identified leucine-rich repeats and immunoglobulin-like domains 1 (LRIG1) as a novel binding partner for VISTA that functions independently of pH, further contributing to CD8+ T cell dysfunction and tumor immune evasion." (PMID 41486149, 2026). "The analysis revealed that in the training set, the expression of BANF1, CDK2AP2, DDT, LRIG1, MRPL4, and S100A13 was significantly upregulated in tumor samples, and the expression of EPS8, NUCB2, PAF1, PMP22, RABGAP1L, and USO1 was higher in control samples (p < 0.05)." (PMID 41000388, 2025). "LRIG1 staining was negative in 1 (1%) tumor, and the staining intensity was weak in 4 (4%), intermediate in 75 (78%), and strong in 16 (17%); 2 (2%) had 26–50% positive cells, 5 (5%) had 51–75% positive cells, and 86 (92%) had 76–100% positive cells." (PMID 38918827, 2024). "Nonetheless, high LRIG1 expression is not consistently favorable and it has been suggested that its function can be either tumor-promoting or suppressive depending on the cellular context." (PMID 38918827, 2024). "LRIG1, the founding member of the LRIG (leucine-rich repeat and immunoglobulin-like domain) family of transmembrane proteins, is a negative regulator of receptor tyrosine kinases and a tumour suppressor." (PMID 35440669, 2022). "For example, the tumour suppressor and stem cell marker Lrig1 is a negative regulator of the epidermal growth factor receptor (EGFR) family." (PMID 36420140, 2022). "The absence of Lrig1 led to decreased presence of flat atypia and formation of larger invasive tumours." (PMID 34385275, 2022).
tumor (continued). "Assessment of Ki67 expression in NTCU-induced lesions showed that Lrig1 depletion leads to abnormally high proliferative rates in early flat atypia lesions, but not in dysplasia or invasive tumours." (PMID 34385275, 2022). "The higher levels of LRIG1 expression was not also related to positive HPV status and tumor progression assessed by its association with degree of differentiation." (PMID 33461538, 2021). "Expression of CK19, SOX9, LGR5, and LRIG1 in MCC and normal human skin was studied by immunohistochemistry, and the staining patterns or intensities were statistically correlated with patient, tumor, MCPyV, and survival parameters." (PMID 34331569, 2021). "In addition, LRIG1 is known to be down-regulated in non-small cell lung cancer (NSCLC), and even highlighted to serve as a tumor suppressor in NSCLC." (PMID 33893245, 2021). "However, the mRNA levels of CTSL, HNRNPK, LRIG1, and OSBPL5 were significantly downregulated in the tumor tissues compared to those observed in normal tissues." (PMID 35284334, 2021). "MSI2 can regulate tumour progression through PTEN, Smad3, TGF-β, LRIG1 and others." (PMID 32606289, 2020). "Lentiviral-mediated LRIG1 overexpression in AR− PCa cells, Du145 and PPC-1, inhibited tumor incidence and/or tumor growth (weight) in NOD/SCID mice, which was associated with decreased cell proliferation (Ki-67+ cells) and slightly increased cell death (cleaved lamin A+ cells) in endpoint tumors." (PMID 31792211, 2019). "A majority of the 70 tumours showed LRIG1 and LRIG2 expression in >50% of cells and demonstrated no or low LRIG3 expression." (PMID 28841699, 2017). "The leucine-rich repeats and immunoglobulin-like protein 1 (LRIG1), which is a negative regulator of EGFR, are tumor suppressors that inhibit receptor tyrosine kinases and may be related to chemoresistance." (PMID 29230082, 2017). "The different tumor types also had different effects on CD26 expression: CD26 expression was unchanged when LGR5+ cells were targeted, was upregulated on targeting of LGR6+ cells, and was downregulated by targeting LRIG1+ cells." (PMID 26771241, 2016). "Statistical analysis demonstrated that the LRIG1 protein levels were highly correlated with the clinical characteristics including pathological type, differentiation status, and tumor stage, but not with sex or age in both cohorts." (PMID 26632716, 2015). "LRIG1, the best-studied LRIG family member, negatively regulates the signaling pathways mediated by ERBB, MET and RET receptor tyrosine kinases, and is suggested to be a tumor suppressor." (PMID 25353163, 2014). "Compared with corresponding nonneoplastic tissue, the expression of LRIG1 appeared downregulated in all of the tumor." (PMID 24314030, 2013). "Five genes with tumor suppressing properties, i.e. SPRY4 (Sprouty homolog 4), DUSP4 and DUSP6 (dual-specificity phosphatases 4 and 6), LRIG1 (Leucine-rich repeats and Ig-like domains 1) and PHLDA1 (Pleckstrin homology-like domain family A, member 1), were upregulated by KGF (1.5–2.1 fold)." (PMID 22427941, 2012). "As predicted, expression of Lrig1 and MAP4 was markedly decreased in tumours." (PMID 18657901, 2008). "The data from the SCC lines make two predictions about marker expression in primary tumours: that markers that are co-expressed in the basal layer of normal epidermis are not co-expressed in SCCs; and that downregulation of MAP4 and Lrig1 is a characteristic feature of SCCs." (PMID 18657901, 2008). "While Lrig1 and MAP4 expression was decreased in tumours, MCSP expression was upregulated." (PMID 18657901, 2008). "Whereas Lrig1 and MCSP are co-expressed in the basal layer of normal epidermis, MCSP positive cells in tumours lacked Lrig1 expression." (PMID 18657901, 2008). "Increased LRIG1 copy number as detected by FISH was associated with increased mRNA and protein levels in tumours compared to non-neoplastic breast tissue, as determined by quantitative RT-PCR and western blot analysis." (PMID 16168117, 2005).
tumor (continued). "In group B, five of the nine tumours overexpressed the LRIG1 protein compared to their matched non-neoplastic tissues as analysed by western blotting." (PMID 16168117, 2005). "A parallel FISH analysis including 10 tumours of a different tissue origin showed no aberrations of LRIG1 gene copy numbers in these tumours (ongoing study, data not shown)." (PMID 16168117, 2005). "As seen by quantitative RT-PCR analysis, two out the three analysed tumours with increased LRIG1 copy number (in group B) showed higher expression of LRIG1 mRNA than the matched non-neoplastic breast tissues." (PMID 16168117, 2005). "The role of LRIG1 as a part of a group of proteins that help desensitize receptor tyrosine kinase (RTK) signalling makes it important to study the expression and role of LRIG1 in tumours in which the ERBB receptors have clinical relevance." (PMID 16168117, 2005). "When divided into groups of high- and low-expressing tumours (median used as cutoff level), a Kaplan – Meier analysis showed a tendency for a nonsignificant survival benefit for patients with high LRIG1-expressing tumours." (PMID 14520461, 2003). "We did not identify a reciprocal event in the tumour with the PAK2::LRIG1 fusion, which might suggest it is expressed below the level of detection or it is not generated." (PMID 41419736, 2025). "Anti-LRIG1 monoclonal antibodies disrupt the interaction between VISTA and LRIG1, resulting in an increased proliferation of immune cells, increased polarization of M1-type macrophages, and an increase in pro-inflammatory cytokines, particularly IFN-γ, which promotes anti-tumor effects." (PMID 39742253, 2024). "However, the absence of LRIG1 led to significantly larger tumours than those in mice with active LRIG1 expression (Kruskal–Wallis test, p=0.0002)." (PMID 34385275, 2022). "Meanwhile, the LRIG1 expression was significantly lower in cancer tissues than normal ones and the same result was detected with no heterogeneity in subgroup analysis based on the type of tumor." (PMID 33461538, 2021). "LRIG1 copy number ratios were not correlated with tumor size." (PMID 32448168, 2020). "In addition, it will be important to determine whether tumour initiation is a general feature of basal cells with high β1-integrin levels, or whether a combination of markers such as CD44, MCSP and Lrig1 will allow further enrichment." (PMID 18657901, 2008). "Two of the tumours without increased LRIG1 copy number also had lowered EGFR expression." (PMID 16168117, 2005). "Also, this Lrig1 mAb may not be beneficial for anti-cancer therapy because the function of Treg cell is an immunological barrier in the tumor microenvironment." (PMID 37666819, 2023). "Hence, we propose that the increased LRIG1 copy numbers previously observed by FISH in most cases may reflect a general polyploidy of the tumor cells rather than specific increases in the LRIG1 gene dosage." (PMID 32448168, 2020). "However, dermal CD26 expression is upregulated in the stroma of Lgr6 but not Lgr5 or Lrig1 tumours." (PMID 29807713, 2018). "Thus our results indicate that patients with HPV-positive, non-keratinizing tumours with high LRIG1 expression might have the best prognosis." (PMID 28841699, 2017). "Therefore, it appears that although LRIG1 may possess a tumor suppressive function in ccRCC, it does not appear to be an important prognostic factor in RCC." (PMID 22554477, 2012). "We first confirmed that Lrig1 is not expressed in the AOM/DSS-specific squamous cell cluster, but only in the tumor cell cluster, in our scRNA-seq data." (PMID 35600339, 2022). "The present data revealed that there was not any correlation between LRIG1 expression and bilateral and peritoneal CRC metastasis (P > 0.05) and also with age, synchronous or metachronous CRC or primary tumor location (P > 0.05)." (PMID 33461538, 2021).